FAM114A1 (family with sequence similarity 114 member A1)
Description:
May play a role in neuronal cell development.
Synonyms: NOXP20
Tractability: PROTAC: ubiquitination databases record sites on it; its protein half-life has been measured.
Gene: Protein-coding gene on chromosome 4 (38,867,677 to 38,945,740, forward strand). Ensembl gene ENSG00000197712.
Subcellular location: Cytoplasm
Subcellular location (Human Protein Atlas): Cytosol; Golgi apparatus; Nucleoplasm
Gene Ontology:
Molecular function: protein binding
Cellular component: cytosol; Golgi apparatus; nucleoplasm; cytoplasm
Genetic constraint (gnomAD): Loss-of-function variants: 57 observed, 61.84 expected, observed/expected ratio (o/e) 0.92, 90% interval 0.74 to 1.15. The upper end of that interval is the gene's LOEUF score, 1.15, which puts it in group 5 of 6, group 1 being the genes least tolerant of losing a copy. Missense variants: 620 observed, 682.31 expected, observed/expected ratio (o/e) 0.91, 90% interval 0.85 to 0.97. Synonymous variants: 245 observed, 256.5 expected, observed/expected ratio (o/e) 0.96, 90% interval 0.86 to 1.06.
Homologues: Orthologues: chimpanzee FAM114A1 (99% identical), macaque FAM114A1 (96% identical), guinea pig FAM114A1 (86% identical), pig FAM114A1 (83% identical), dog FAM114A1 (82% identical), rabbit FAM114A1 (80% identical), rat Fam114a1 (79% identical), mouse Fam114a1 (78% identical), rat Fam114a1l1 (77% identical), tropical clawed frog fam114a1 (51% identical), zebrafish fam114a1 (50% identical), Drosophila melanogaster CG9590 (20% identical). Paralogues in human: FAM114A2 (39% identical).
Diseases named in the same sentence as FAM114A1 in open-access papers:
FAM114A1 is named in the same sentence as 34 diseases in open-access papers, as found by Europe PMC text mining. Sharing a sentence is not in itself a finding about the gene and the disease. The quoted sentences say what the papers report.
ankylosing spondylitis (2 papers, 2022). An autoimmune chronic inflammatory disorder characterized by inflammation in the vertebral joints of the spine and sacroiliac joints. "FAM114A1 has multiple SNPs associated with human inflammatory diseases such as ankylosing spondylitis and host immune response to bacterial infection." (PMID 35671117, 2022).
acute coronary syndrome (1 paper, 2022). Signs and symptoms related to acute ischemia of the myocardium secondary to coronary artery disease. "In another independent study, one FAM114A1 SNP (rs1873197; P = 3.32 × 10–6) was identified as a CAD-associated locus with CAD diagnosis (e.g., MI, acute coronary syndrome, chronic stable angina, or coronary stenosis > 50%)." (PMID 35671117, 2022).
allergic disease (1 paper, 2025). An immune response that occurs following re-exposure to an innocuous antigen, and that requires the presence of existing antibodies against that antigen. "FAM114A1 is less well characterized but has been linked to neuronal development, podocyte cytoskeleton maintenance and possibly B-cell function, with emerging data suggesting associations with allergic disease, potentially via angiotensin II–related pathways." (PMID 41476961, 2025).
cardiac hypertrophy (1 paper, 2022). "This antihypertensive effect from Fam114a1 loss may contribute to the reduction of cardiac hypertrophy." (PMID 35671117, 2022). "Ischemia-induced cardiac hypertrophy was significantly blunted in Fam114a1–/– mice 20 days after MI." (PMID 35671117, 2022).
coronary artery disease (1 paper, 2022). "FAM114A1 was recently identified as a candidate gene involved in coronary artery disease in a transcriptome−wide association study." (PMID 36211422, 2022).
fibrosis (1 paper, 2022). the formation of excess fibrous connective tissue in an organ or tissue in a reparative or reactive process. "We used a global Fam114a1-KO mouse model to demonstrate that deletion of FAM114A1 antagonizes pathological cardiac remodeling, including cardiac fibrosis, CM hypertrophy, and inflammation in vivo using Ang II and MI models." (PMID 35671117, 2022). "Homozygous KO of Fam114a1 (Fam114a1–/–) in the mouse genome reduces cardiomyocyte hypertrophy, inflammation, and cardiac fibrosis while restoring cardiac function in angiotensin II–induced (Ang II–induced) and MI-induced HF mouse models." (PMID 35671117, 2022). "Under cardiac stresses, increased FAM114A1 may promote cardiac fibrosis and remodeling through the FAM114A1/AGTRAP/AT1R axis in CFs." (PMID 35671117, 2022).
idiopathic dilated cardiomyopathy (1 paper, 2022). Decreased function of the heart associated with cardiac enlargement and congestive heart failure, of unknown cause. "An independent data set of human samples also shows increased expression of FAM114A1 mRNA in the failing hearts of patients with idiopathic dilated cardiomyopathy (IDCM) and ischemic cardiomyopathy (ICM) compared with healthy participants." (PMID 35671117, 2022).
ischemia (1 paper, 2022). A hypoperfusion of the BLOOD through an organ or tissue caused by a PATHOLOGIC CONSTRICTION or obstruction of its BLOOD VESSELS, or an absence of BLOOD CIRCULATION. "Multiple pathological cardiac stresses induce FAM114A1 such as Ang II stimulus and ischemia." (PMID 35671117, 2022).
myocardial infarction (1 paper, 2022). Gross necrosis of the myocardium, as a result of interruption of the blood supply to the area, as in coronary thrombosis. "Here, we found that a functionally unannotated human myocardial infarction–associated (MI-associated) gene, family with sequence similarity 114 member A1 (FAM114A1), is induced in failing human and mouse hearts compared with nonfailing hearts." (PMID 35671117, 2022).
vitiligo (1 paper, 2021). Generalized well circumscribed patches of leukoderma that are generally distributed over symmetric body locations and is due to autoimmune destruction of melanocytes. "We discovered that Fam114A1 is closely related to the growth of vitiligo melanocytes by affecting the proliferation, apoptosis, migration, and melanin synthesis of melanocytes and has a reverse effect on the expression of RACK1 protein." (PMID 34837888, 2021). "We also compared the expression of Fam114A1 protein in the normal region of vitiligo (MCV-N), the marginal lesion of vitiligo (MCV-L), and the vitiligo cell line PI3V and the melanocytes (MC) in normal people." (PMID 34837888, 2021). "Fam114A1 is highly expressed in the skin of vitiligo skin lesions and is also highly expressed in melanocytes at the edges of the skin lesions and normal parts of the patient." (PMID 34837888, 2021). "The expression of Fam114A1 protein in vitiligo epidermal tissues was higher than that in normal skin tissue." (PMID 34837888, 2021). "Next, we used immunofluorescence technology to confirm the expression of Fam114A1 in melanocytes, and immunohistochemistry was performed to detect the expression of Fam114A1 in vitiligo epidermal tissues and normal skin tissues." (PMID 34837888, 2021). "According to these theories, we believe that the negative regulation of RACK1 protein through Fam114A1 protein may have a role in the pathogenesis of vitiligo." (PMID 34837888, 2021). "In summary, the Fam114A1 protein can affect the apoptosis, migration and melanin synthesis ability of melanocytes, may be involved in the death of melanocytes in vitiligo, and play a certain role in the pathogenesis of vitiligo." (PMID 34837888, 2021). "We found that the expression of Fam114A1 in vitiligo melanocytes (MCV-L, MCV-N, PI3V) was higher than that in normal melanocytes, and the biological function of melanocytes was significantly affected when the Fam114A1 gene was silenced." (PMID 34837888, 2021). "In order to analyze the expression of Fam114A1 in melanocytes from different sources, we cultured melanocytes (see our previous studies) collected from the normal region of vitiligo (MCV-N), marginal lesion of vitiligo (MCV-L), the vitiligo cell line PI3V, and normal human melanocytes (MC)." (PMID 34837888, 2021).
cancer (4 papers, 2017 to 2025). A tumor composed of atypical neoplastic, often pleomorphic cells that invade other tissues. "FAM114A1, the family with sequence similarity 114 member A1, has been associated with several diseases such as heart disease and cancers." (PMID 39770537, 2024).
tumor (3 papers, 2022 to 2025). "Many pathways and cell populations (such as fibroblasts) are involved in the tumor-promoting role of FAM114A1, suggesting that FAM114A1 is a pleiotropic protein." (PMID 41249116, 2025). "As expected, FAM114A1-KD tumors contained significantly fewer tumor cells with detectable FAM114A1, indicating the robustness of FAM114A1-KD at the time of harvest." (PMID 41249116, 2025). "To experimentally validate these observations, we performed IHC on FFPE tumor samples from 109 patients with TNBC and found that higher FAM114A1 expression was associated with significantly less CD8+ T-cell infiltration." (PMID 41249116, 2025). "CD8+ T-cell depletion significantly restored tumor progression in the FAM114A1-KD group, suggesting that FAM114A1-mediated immune suppression is critical for its tumor-promoting function." (PMID 41249116, 2025). "Treatment with these FAM114A1 ASOs significantly enhanced the tumor immune killing effect in our coculture system." (PMID 41249116, 2025). "To distinguish the effects of FAM114A1 on cell cycle progression from its immunosuppressive role, we developed an in vitro tumor sphere/immune coculture assay." (PMID 41249116, 2025). "Upregulation of these FAM114A1-mediated pathways suppresses tumor antigen presentation and consequently attenuates antitumor immunity in TNBC." (PMID 41249116, 2025). "Inducing FAM114A1-KD together with anti-PD-1 treatment significantly inhibited tumor progression." (PMID 41249116, 2025). "To investigate whether E2F4 is also involved in FAM114A1-mediated tumor immune evasion, we extensively explored the role of E2F4 in this context." (PMID 41249116, 2025). "In support of this notion, reduced MTDH expression was observed in tumor cells with FAM114A1-KD." (PMID 41249116, 2025). "We found that FAM114A1 overexpression reduced p85α–p110α interactions in tumor cells." (PMID 41249116, 2025). "Tumor cells with FAM114A1-KD presented significantly lower E2F4 protein levels in nuclear fractions, suggesting that FAM114A1 may facilitate E2F4 nuclear translocation." (PMID 41249116, 2025). "Pathway enrichment analysis revealed that PI3K-related pathways were enriched in control cells, and antigen processing and presentation pathways were enriched in FAM114A1-KD tumor cells, revealing that FAM114A1 may be involved in these pathways." (PMID 41249116, 2025). "Overall, targeting FAM114A1 in tumor cells sensitizes TNBC to ICB therapy." (PMID 41249116, 2025). "Overall, these findings indicate that FAM114A1 may activate PI3K/AKT signaling to suppress tumor cell antigen presentation." (PMID 41249116, 2025). "As expected, induced FAM114A1-KD also sensitized tumor cells to immune killing." (PMID 41249116, 2025). "First, we found that E2F4 formed puncta in tumor cells and that the proportion of cells with puncta significantly increased upon FAM114A1-KD, suggesting that FAM114A1 inhibited E2F4 condensate formation." (PMID 41249116, 2025). "Moreover, the FUSCC dataset (SRP157974) was used again to compare further characteristics, such as tumor stage, PDCD1, and CD274, in the FAM114A1-high/low patient groups." (PMID 41249116, 2025). "In summary, although FAM114A1 is involved in cell cycle regulation, its antigen presentation inhibition and consequent immunosuppressive effects are independent of its intrinsic effects on tumor cells." (PMID 41249116, 2025). "On the basis of B2m-KD, FAM114A1-KD did not further enhance the immune killing of tumor cells." (PMID 41249116, 2025). "To distinguish whether FAM114A1 upregulation is a hypoxia related or predominantly related to VEGFA activation, we explored into conditions involving non-hypoxia related VEGFA activation such as in cell growth, apoptosis, cell proliferation and tumor development." (PMID 36006949, 2022).
tumor (continued). "Furthermore, FAM114A1-low patients presented significantly greater CD8+ T-cell infiltration, independent of tumor stage, and CD274 and PDCD1 expression, according to multivariate logistic regression analysis." (PMID 41249116, 2025). "Tumor stage and CD274 expression were not correlated with the FAM114A1 level." (PMID 41249116, 2025).
heart disease (2 papers, 2022 to 2024). "Our work indicates the importance of FAM114A1 in the pathogenesis of cardiac remodeling and establishes FAM114A1 as a potentially novel therapeutic target for heart disease with high safety upon complete inactivation." (PMID 35671117, 2022). "This study confirms the safety of complete inactivation of FAM114A1 to be used as a potential therapeutic approach to treat cardiac diseases." (PMID 35671117, 2022). "Therefore, we investigated the role of FAM114A1 in heart disease and its potential as a therapeutic target for HF treatment." (PMID 35671117, 2022).
FAM114A1 also shares sentences with these, for which no sentence is quoted: glioma (2 papers); atopic dermatitis (1); bacterial infection (1); breast carcinoma (1); cardiovascular disease (1); cervical cancer (1); colorectal cancer (1); coronary stenosis (1); endometrial cancer (1); hepatocellular carcinoma (1); Hypertension (1); inflammatory bowel disease (1); ischemic cardiomyopathy (1); liver cancer (1); lung carcinoma (1); ovarian carcinoma (1); pancreatic cancer (1); renal carcinoma (1); stomach cancer (1); thyroid cancer (1); viral infections (1).